CD4 (CD4 molecule)
Diseases named in the same sentence as CD4 in open-access papers (continued):
Sharing a sentence is not in itself a finding about the gene and the disease.
tumor (continued). "The fraction of Ki-67+ cells correlated with the fraction of HLA-DR+ cells in the DP CD4+ T cell population in both tumor types, however, the 2 markers were not always coexpressed." (PMID 35439168, 2022). "Moreover, given that effective T cells such as activated CD4 and CD8 T cells play a pivotal role in the tumor microenvironment, we also calculated their correlations with TIP score, and we found they were both correlated with TIP score positively." (PMID 35493471, 2022). "Using this technique, we were able to isolate 29 tumor specific T-cell clones (11 CD8+, 18 CD4+)." (PMID 35468205, 2022). "After CD4+ T cells are mainly activated by activated DCs, they can directly recognize and kill MHC-II+ tumor cells as well as recruit and activate more NK cells, DCs, and CD8+ T cells, and enhance the tumor cell-killing ability of CTLs." (PMID 36072581, 2022). "Regarding the overall levels of tumor ICI, immune cells with high-level infiltration included CD4+-central memory T cells, CD56+-suspicious natural killer cells (CD56+-NK cells), immature dendritic cells, myeloid suppressor cells (MDSCs), and CD8+-central memory T cells." (PMID 35756659, 2022). "αPD-1 and αPD-L1 decreased CD4/CD8 T cell ratio in young and aged co-culture conditions versus isotype controls, consistent with supporting CD8+ T cell expansion, which is favorable to anti-tumor immunity." (PMID 36876140, 2022). "Examination of lineage-specific marker expression revealed four principal clusters corresponding to tumor and glia (using the SOX2, OLIG2, GFAP markers), lymphoid cells (CD45, CD3, CD8, and CD4), myeloid cells (CD45, PU.1, CD163, CD68, and CD11b), and endothelial cells (CD31)." (PMID 35973991, 2022). "In summary, this report demonstrates that Tr1 cells, not only cTreg cells, are present at the tumor site in the early stages of the tumor development and that the disruption of the CD49b/CD29 axis prevents tumor growth by at least targeting CD4+T and CD8+T cells function." (PMID 35860556, 2022). "The tumour microenvironment acts as a stage for the interplay between anti-tumour-immune response cells such as CD8 + T cells, NK cells, CD4 + Helper T cells and M1 macrophages and immunosuppressive cells such as myeloid-derived suppressor cells (MDSCs) and regulatory T cells (Tregs)." (PMID 36284306, 2022). "Moreover, the combo gel treatment also significantly stimulated programmed death-ligand 1 (PD-L1) upregulation on tumor cells, consistent with the enhanced expression potential of IFNγ by CD8+ and CD4+ TILs." (PMID 35780226, 2022). "Given that the ideal TIL population to expand is tumour-specific CD8+ T-cells, it may be better for TIL cultures to have a low CD4/CD8 ratio." (PMID 35158816, 2022). "Moreover, more CD4+ and CD8+ T cells infiltrated the tumor site and contributed to the immune-mediated death of tumor cells after treatment with curcumin." (PMID 36615387, 2022). "Treg cells in the IMQDC-Ag-treated group showed a CD4 effector phenotype similar to chemoimmunotherapy, as opposed to the induced Treg cells observed in the tumor control and following TPI treatment." (PMID 36090972, 2022). "In the current work, we have observed similar changes in the tumor microenvironment with increased scores for CD8+ and CD4+ lymphocyte functions, as well as for antigen-presenting cells such as dendritic cells, which were further enhanced in mice with pre-existing anti-HSV-1 immunity." (PMID 36366425, 2022). "The expressions of CCR1, PNOC, and VIP genes were significantly correlated with tumor purity, B cell infiltration, CD8+T cell infiltration, CD4+T cell infiltration, macrophage infiltration, neutrophil infiltration and dendritic cell infiltration, and the differences were statistically significant." (PMID 35174205, 2022). "Tumour infiltrating conventional DCs (cDC1 and cDC2) scan and phagocytose tumour antigens; and subsequently migrate to secondary lymphoid tissues to prime naïve CD8+ and CD4+ T cells." (PMID 35355992, 2022).
tumor (continued). "In addition, tumor infiltrating CD8+, CD4+ T cells, and NK cells are often found to express high levels of TIGIT, the interaction of which with CD155 is known to suppress the antitumor effect of these cells." (PMID 36268020, 2022). "Combination therapy failed to improve survival in both CD4−/− and CD8−/− tumor-bearing mice (respectively) indicating the enhanced antitumor response seen with the combination therapy is both CD4+ and CD8+ T cell-dependent." (PMID 36302761, 2022). "A decreased CD4/CD8 ratio (p = 0.051) and comorbidity with a tumor (p = 0.057) were not statistically linked, although the p values were extremely close to 0.05." (PMID 36288019, 2022). "The results showed that CD3+ T cells, CD4+ T cells and CD8+ T cells in CHSY3 expressing “+++” tissues were mainly clustered in the tumour peripheral stroma, with few immune cells penetrating the stroma into the tumor parenchyma." (PMID 35571047, 2022). "In the tumor group, T cell CD8+, T cell CD4+ naive, T cell CD4+ memory activated, T cell follicular helper, NK cell activated, Macrophage M0, Macrophage M1, Macrophage M2, Myeloid dendritic cell resting, and Neutrophil infiltration were higher in proportion (p < 0.05)." (PMID 36685898, 2022). "Besides, our experiments only analyzed the changes in CD4+ and CD8+ TILs infiltration in tumor and spleen tissues, and the effect of the different treatments on other immune cells was not explored." (PMID 35142593, 2022). "We used the BR-Luc syngeneic model to investigate the relation between anti-tumor efficacy and the presence of immune infiltrates, including the impact on FRβ-expressing TAMs and CD3+, CD4+ and CD8+ T cells, accompanying treatment with the pyrrolo[2,3-d]pyrimidine antifolate inhibitor AGF94." (PMID 35790779, 2022). "They found that murine CD4+ Treg isolated from the TME upregulated GzB, but not GzA, and that perforin and GzB deficiency were essential in dampening anti-tumor responses in vivo." (PMID 35493508, 2022). "Cytotoxic T lymphocyte-associated antigen-4 (CTLA-4), also known as CD152, is a membrane protein expressed on CD4+ and CD8+ T cells that is involved in the downregulation of T cell immune response at the tumor site upon interaction with CD80/B7.1 and CD86/B7.2 on APC." (PMID 35625811, 2022). "In TNBC patients, the frequency of terminally exhausted CD4+ T cells and CD8+ T cells, characterised by the expression of CD39, is highly correlated between the primary tumour and the peripheral blood, potentially reflecting an intimate relationship between T cell suppression at both sites." (PMID 36139665, 2022). "Among the clinicopathological and genomic characteristics, NMP exhibited the strongest negative correlation with DTICs, including CD3+ (P < 0.001), CD4+ (P = 0.065), CD8+ (P = 0.004), and FOXP3+ (P = 0.033) cells in the central tumor area (marked by a red arrow)." (PMID 35443723, 2022). "Our data demonstrate that ICOS is upregulated on CD4 and CD8 T cells in the peripheral blood and tumor following radiation therapy, and that the combination of a novel ICOS agonist antibody with radiation therapy results in tumor control." (PMID 36056093, 2022). "TOX expression has been analyzed in cutaneous T-cell lymphomas (CTCL) and noticed that its expression is not tumor-specific or restricted to CD4+ CD8- phenotype." (PMID 36741360, 2022). "The profile of tumor infiltrating immune cells was analyzed by FACS and the results revealed that the percentage of immunosuppressive CTLA4+ or PD-1+ on CD8+ T cells and CD4+CD25+Foxp3+ Tregs was significantly reduced in nCHI3L1 Ab treatment group compared to that in the IgG group." (PMID 34987649, 2022). "The number of CD4+ T cells in the primary tumors, tumor-draining LNs, and spleens of tumor-bearing LECMHC-II−/− mice were not different from controls." (PMID 36362253, 2022).
tumor (continued). "For responding cells, the average number of divisions they undergo (PI) was not different among experimental conditions for CD4+ T cells (p-value = 0.22) but reduced in CD8+ T cells exposed to tumor-conditioned media (p-value = 0.0077)." (PMID 35418177, 2022). "In contrast, the tumor in our case regressed to a minimal size after increased CD4 counts without surgery, although it remained latent." (PMID 35141174, 2022). "The population of CD8+ T cells but not NK cells or CD4+ T cells in CD45+ cells from the SENP3–9A tumor tissues were much more than that from the SENP3-WT tumors in C57BL/6 mice." (PMID 35869062, 2022). "Importantly, CD4+, CD8+, and CD11c+ immune cell infiltration into tumor tissues was significantly improved in combination therapy with respect to radiotherapy alone." (PMID 36091031, 2022). "Mounting evidence over the past decade suggests that the major TIL subpopulations (CD4, CD8, and CD19/20) encompass varying subset balances with suppressive (pro-tumor) or effector (anti-tumor) phenotypes whose functions are influenced by the surrounding TME10." (PMID 35473931, 2022). "According to analyses of the Tumor Immune Estimation Resource (TIMER) database, six types of immune cells (B cells, CD8 + T cells, CD4 + T cells, macrophages, neutrophils, and dendritic cells) were associated with PROS1 expression and prognosis in patients with LGG." (PMID 35879775, 2022). "We did not found differences in the T-cell activation or CD4/CD8 ratio depending on the tumor cell/lysates treatments." (PMID 35684322, 2022). "Moreover, B cells in TLSs can function as antigen-presenting cells; they highly express the co-stimulatory molecules CD86 and CD80 and facilitate tumor antigen-specific T-cell responses, including CD8+ TIL and CD4+ TIL responses." (PMID 35663939, 2022). "In preclinical models, niraparib has been shown to promote tumour immune cell infiltration by CD4+ and CD8+ T cells, induce activation of interferon signaling and work synergistically to decrease tumour volume when combined with the PD-L1 checkpoint inhibitor pembrolizumab." (PMID 36230543, 2022). "Notably, we encountered significant intra- and inter-model variability in the engrafted population of total human T cells (CD3+ cells) including both CD4+ and CD8+ subsets and tumor-infiltrating populations." (PMID 36095023, 2022). "Furthermore, the animal study revealed that the CD4+ TLEX-CD8086 significantly inhibited tumor growth and prolonged survival of tumor-bearing mice than other formulations did in both protective and therapeutic models." (PMID 36466863, 2022). "The presence of CD4+ and CD8+ T cells and ADCC were required for complete tumor regression." (PMID 35710296, 2022). "Tissue staining showed that TMEM170B had strong positive correlations with tumour-infiltrating CD4+ and CD8+ cells, and negative correlations with MDSCs." (PMID 35601487, 2022). "YAP1 may promote tumor progression through immunosuppression, particularly by suppressing the infiltration of CD8+ T lymphocytes, CD4+ Th1 cells, T follicular helper cells, NKT cells, and activated NK cells, as well as recruiting MDSCs and CAFs in pan-cancer." (PMID 36479120, 2022). "Mainly, CD4+ and CD8+ T-cells are responsible for preventing tumor growth and cancer development." (PMID 35892821, 2022). "To summarize, TDO2+ myofibroblasts were mainly located distally from tumor nests, and these cells attracted CD4+ T cells and CD8+ T cells through the CXCL9/CXCL10/CXCL11/CXCR3 axis, which may have prevented T cells from accessing tumor nests." (PMID 35972800, 2022). "Indeed, the adaptive immune response involves B lymphocytes (CD20+) and T cells (CD3+), including CD4+ T-helper 1 and cytotoxic T lymphocytes (CD8+) which counteract tumor development and progression." (PMID 36010653, 2022).
tumor (continued). "Cluster 7, which contained the Th17 subset of CD4+ T cells (CD3+, CD4+, CD196+, HLA-DR), was significantly more abundant in tumor tissues of patients with moderate-to-severe inflammation and fibrosis than in tumor tissues of patients with mild inflammation and fibrosis." (PMID 36661665, 2022). "Analysis of the interactions between MF-C1-TDO2 myofibroblasts and CD8+ T or CD4+ T cells using the CellPhoneDB revealed that, in comparison with MF-C2-ELN myofibroblasts, MF-C1-TDO2 myofibroblasts in tumor tissue had stronger chemotaxis toward both CD8+ T cells and CD4+ T cells." (PMID 35972800, 2022). "Due to the high immunogenicity of neoantigens, tumor vaccines could activate and expand antigen-specific CD4+ and CD8+ T cells to intensify anti-tumor immunity." (PMID 36263174, 2022). "Consistent with the enhanced tumor suppression, immunophenotyping of both tumors from mice receiving different treatments demonstrated that mice treated with KYNase and Dox formulated in the hydrogel elicited significantly more CD8+ and CD4+ TILs." (PMID 35780226, 2022). "As most tumor cells do not express MHC-II, CD4+ Th cells cannot sense tumor antigens or tumor cells directly." (PMID 35326515, 2022). "To confirm whether PD-1–laIL-2 can increase the effector function of some subsets of TILs, we sorted CD4+, PD-1–CD8+, PD-1+TIM3–CD8+, and PD-1+TIM3+CD8+ T cells from the tumor and treated them with PD-1–laIL-2 in the presence of irradiated A20 tumor cells." (PMID 35104810, 2022). "We would propose that treatments would focus on generating a tumor specific CD4 and CD8 T cell population in the tumor, and may rely on therapies that can bring suboptimal T cells into the tumor to become functional anti-tumor effectors." (PMID 35937775, 2022). "CD4 T cells recognize homocitrullinated epitopes but the anti-tumor effect may be mediated by a bystander effect of CD4 activation of other effector cells such as CD8, NK cells or macrophages or, CD4s may act directly via induction of MHC-II on tumor cells." (PMID 35464453, 2022). "Therefore, SI-2 promoted the establishment of an antitumor immune environment at least in part by recruiting cytotoxic CD4+, CD8+ T cells, and CD56+ cells into the tumor tissue." (PMID 36316775, 2022). "CD8+ and CD4+ T cells, which play a core role in the immunoediting process, distinguish these non-self-epitopes of tumor cells displayed by MHC class-I and MHC class-II molecules respectively from normal self-antigens." (PMID 35154149, 2022). "Moreover, the tumor immune environment includes multiple immune populations, and patient prognosis depends on CD8 cells as well as CD4 cells, Treg cells, and myeloid cells, including macrophages, neutrophils, and myeloid-derived suppressor cells." (PMID 36437964, 2022). "Furthermore, we observed marked increases in the percentages of IFN-γ-producing CD4+ and CD8+ T cells in K7M2 tumors, suggesting that tumor-infiltrating T lymphocytes were activated upon c-Myc inhibition." (PMID 35292660, 2022). "We previously demonstrated that RT39, but not its inactive point mutated form RT39M, exhibited a selective cytotoxicity toward Sézary patients’ primary tumor CD4+ cells ex vivo, while sparring non-malignant lymphocytes." (PMID 36230895, 2022). "In the HPV16 tumor-bearing mice, compared with those of the PBS blank control group and AD-NC group, the CD4+/CD8+ ratio in the vaccine group were significantly reduced, while the ratio of CD8+ lymphocytes was significantly increased compared with those of the PBS blank control group (P < 0.05)." (PMID 35197089, 2022). "Third, based on the limited data, CC-01 did not significantly altered the infiltration of CD4+ or CD8+ T cells in tumor but showed trend of decrease in exhausted T cells." (PMID 35058524, 2022).
tumor (continued). "Tumor progression in this model was shown to be inhibited even in the presence of CD4+ T cells alone and absence of CD8+ T cells, and that was mediated via the tumor necrosis factor receptor 1 (TNFR1) signaling and the interferon-γ (IFN-γ) pathways." (PMID 36430404, 2022). "However, CD3, CD4 and CD8 expression was generally detected across the whole tumor and normal tissues in PTC-W." (PMID 35720279, 2022). "HFD-fed mice showed a marked reduction in CD4+ T cell number in the blood after tumor inoculation; no such difference was observed in the CD-fed mice." (PMID 36611881, 2022). "More importantly, we observed enrichment of potentially exhausted and suppressive immune subsets in tumours: Foxp3+CD152+TIGIT+CD4+ regulatory T cells (Treg) (C4), PD1+CD103+CD45RO+CD8+ resident memory T cells (TRM) (C7) and PD1+ CD45RO+CD4+ memory T cells (C19)." (PMID 35301339, 2022). "In contrast, α-PD-L1 induction of these exhaustion markers did not elevate in CD4+ T cells from spleens, demonstrating that reprogramming tumor-infiltrating lymphocytes (TIL) is the key to improved therapeutic outcomes." (PMID 36969745, 2022). "Biopsy performed after the two cycles of treatment and immunohistochemistry analysis revealed that infiltration of CD4+ T lymphocyte, CD8+ T lymphocyte, and CD68+ macrophage in the tumor microenvironment was significantly increased compared with that before treatment." (PMID 36273133, 2022). "For instance, the interaction between CD80/86 and CTLA-4 on human DCs and CD4+ T cells has been shown to trigger the expression of indoleamine 2,3-dioxygenase (IDO) in DCs, an enzyme that suppresses T cell proliferation and induces tumor immunosuppression." (PMID 35269922, 2022). "Furthermore, CD4+ CD25+ Foxp3+ Tregs are currently considered one of the most important immune cell subsets that promote immune escape and tumor growth in the immunosuppressive TME." (PMID 34968167, 2022). "This suggests that although both CD4+ and CD8+ T cells can mediate CD3 bsAb-mediated tumor cell kill, the dynamics of CD4+ and CD8+ T-cell activation or the distribution of CD4+ and CD8+ T cells may differ between in vitro and in vivo settings." (PMID 36271507, 2022). "This could be potentially relevant for others CD4+ T cells in the TME such as Th1-like cells and the immune cell crosstalk in the tumor niche." (PMID 35769460, 2022). "In addition to CD8+ T cells, we also characterized CD4+ T cells, CD20+ B cells, and CD163+ histocytes infiltrating the tumour-related stroma." (PMID 36280845, 2022). "We next inspected tumor-infiltrating T cells, a heterogeneous population that includes effector T cells such as CD8a+ cytotoxic T cells (CTL) and natural killer T cells (NKT), as well as CD4+ helper T cells and Tregs." (PMID 36105861, 2022). "Given that Ibr/Rap skewed CD8 and CD4 TILs towards a TEMRA phenotype, we analyzed gene expression profiles of expanded TILs using a custom panel of over 700 tumor- and immune-related genes on the NanoString nCounter PanCancer Immune profiling platform (NanoString Technologies Inc.)." (PMID 34987640, 2022). "Both HLA-DRA and HLA-DRB1 were underexpressed in NSCLC PBL T cells and overexpressed in NSCLC tumor C11 /C6-LAYN CD8 T cell clusters, C14 CD4/CD8 T-cell clusters, and suppressive tumor Tregs of CD4-C9-CTLA4 cells vs. other tumor-infiltrating Tregs of CD4-C8-FOXP3 cells." (PMID 35804895, 2022). "This lack of consistency is likely due to differences in the compartment studied (peripheral blood vs bone marrow), different immunophenotypic definitions of Tregs (CD4+FoxP3+, CD4+CD25hi, CD4+CD25+FoxP3+, CD4+CD25+CD127−), and interpatient tumor heterogeneity." (PMID 36421358, 2022). "Moreover, the combined treatment with the application of DIM and PD-1 blockade significantly increased the ratio of CD4+ and CD8+ T cells and enhanced IFN-γ secretion, ultimately suppressing tumor growth." (PMID 35773674, 2022).